CETP (cholesteryl ester transfer protein)
Diseases named in the same sentence as CETP in open-access papers (continued):
Sharing a sentence is not in itself a finding about the gene and the disease.
Sepsis (continued). "In this light, the recent reports that CETP inhibition is beneficial in sepsis, at least in mouse models, suggests similar interventions may have beneficial impacts on COVID-19 disease." (PMID 34638523, 2021). "A study assessing human genetics CETP gain-of-function cohorts and humanized mouse models found that inhibition of CETP may improve sepsis outcomes by maintaining HDL levels thereby modulating immunity." (PMID 35071235, 2021). "The activity of CETP was significantly lower in patients with sepsis compared to ICU controls." (PMID 35071235, 2021). "Interestingly, the accumulation of M2 macrophages was observed in adipose tissue and liver, in tissues with high expression of CETP and the lung, as well as in the blood of patients who suffered severe trauma, such as burns or sepsis." (PMID 34367144, 2021). "Our findings suggest that CETP modulates HDL-C levels in sepsis." (PMID 30425299, 2018). "Thus, we investigated the inflammatory profile to understand how CETP is involved in sepsis protection." (PMID 27293313, 2016). "However, whether CETP inhibition is beneficial in more clinically relevant models of sepsis, such as pneumonia, is unknown." (PMID 38646937, 2024). "Additionally, ApoA-I accounts for over 50% of the effects of CETP inhibitors on sepsis." (PMID 37621565, 2023). "Hence, basal changes in plasma total cholesterol and lipoprotein levels, as occurring in the presence of CETP, may significantly alter inflammation and sepsis outcome." (PMID 33500240, 2021). "Although these earlier data suggest that CETP might play a role in LPS transport and metabolism, it is not known whether altered CETP levels in patients is a cause or a consequence or sepsis severity." (PMID 33500240, 2021). "One of the drawbacks of the technique used in earlier in vitro studies comes from the use of purified LPS as a substrate for CETP while circulating LPS is mostly found in host organisms as aggregates/micelles or as part of complex lipid structures derived from bacterial membranes during sepsis." (PMID 33500240, 2021). "Furthermore, lipid transfer proteins such as PLTP and CETP are significantly altered during sepsis." (PMID 35071235, 2021). "Therefore, the deleterious effect of CETP that we could observe in both models of endotoxemia and polymicrobial infection might relate to an indirect role of this protein on sepsis and endotoxemia, independently from LPS transfer." (PMID 33500240, 2021). "Modulation of HDL-C levels by CETP inhibition could be a novel sepsis therapeutic target." (PMID 30736368, 2019). "Therefore, CETP activity plays a critical role in affecting sepsis outcomes." (PMID 30736368, 2019). "However, use of statins did not alter HDL-C levels during sepsis in this cohort (HDL-C median value 33.83 mg/dL WT vs. 29.19 mg/dL CETP variant, P = 0.078, data not shown)." (PMID 30425299, 2018). "Therefore, it is biologically plausible that CETP may be a key driver of the acute decline in HDL-C that occurs in sepsis." (PMID 30425299, 2018). "Given the success of a CETP inhibitor in improving the survival of septic mice, further investigation of the interaction between HDL and sepsis is warranted." (PMID 38603717, 2024). "Here, we show that treatment with the CETP inhibitor (CETPi) anacetrapib reduced mortality from Streptococcus pneumoniae–induced sepsis in APOE*3-Leiden.CETP and APOA1.CETP mice." (PMID 38646937, 2024). "Finally, we showed that CETP inhibition was effective at reducing sepsis mortality even when administered after disease onset, suggesting that CETP inhibition may represent a therapeutic approach for the treatment of sepsis." (PMID 38646937, 2024). "While our in vitro results suggest that CETP inhibition enhances macrophage activation independently of HDL, the relative contributions of HDL-dependent or -independent mechanisms on improved sepsis survival in vivo remain to be determined." (PMID 38646937, 2024).
Sepsis (continued). "Cholesteryl ester transfer protein (CETP), responsible for the transfer of cholesterol between HDL and LDL, has been shown in animal models to be reduced by sepsis or inflammation." (PMID 38015312, 2023). "For CETP inhibitors, we used LDL-C and HDL-C as proxies and observed their protective effects against sepsis." (PMID 37621565, 2023). "Our MR study suggested that ApoA-I and HDL-C had protective effects against sepsis, while HMGCR and CETP inhibitors had therapeutic potential beyond their lipid-lowering function." (PMID 37621565, 2023). "In our research, both the LDL-C and HDL-C proxied CETP inhibitors, which lower LDL-C and elevate HDL-C, can treat sepsis by increasing ApoA-I." (PMID 37621565, 2023). "Our MR study suggested that ApoA-I and HDL-C protected against sepsis, while HMGCR and CETP inhibitors showed therapeutic potential beyond lipid-lowering effects." (PMID 37621565, 2023). "LDL-C and HDL-C proxied CETP inhibitors were found to have a protective effect on total sepsis, with only LDL-C proxied CETP inhibitors showing a suggestively protective effect on sepsis." (PMID 37621565, 2023). "LCAT activity, LCAT concentration and CETP activity were significantly lower, while PLTP activity was significantly higher in ICU sepsis compared to ICU control patients." (PMID 35071235, 2021). "Cholesteryl ester transfer protein (CETP) is an LT/LBP member, but its impact on LPS metabolism and sepsis outcome is unclear." (PMID 33500240, 2021). "Considering these facts, in the present study we aimed at clarifying the role of CETP in the inflammatory response and sepsis after cecal ligation and puncture (CLP), a clinically relevant sepsis model." (PMID 27293313, 2016). "In addition, the survival in control-treated APOA1.CETP mice and APOE*3-Leiden.CETP mice was similar, despite differences in HDL-C levels, suggesting other factors beyond the HDL-C level that contributes to sepsis survival." (PMID 38646937, 2024). "In addition, the mechanisms by which CETP inhibition and HDL improve survival from sepsis remain incompletely understood." (PMID 38646937, 2024). "In cases of Gram-negative-induced sepsis, the release of LPS endotoxin activates Kupffer cells, which exert antibacterial effects by releasing pro-inflammatory cytokines and reducing CETP expression, thereby increasing HDL-C levels in the bloodstream." (PMID 39057711, 2024). "Increased CETP activity would deplete HDL particles of their cholesterol content, induce HDL catabolism, and reduce HDL plasma concentration, which suggests that the observed decrease with sepsis is a compensatory mechanism." (PMID 38015312, 2023). "Another report suggested that cholesteryl ester transfer protein had the ability to disrupt the interplay of bacterial lipopolysaccharide and TLR4 (Toll-like receptor 4), thereby reducing the uncontrolled inflammatory response in sepsis." (PMID 36579569, 2022). "Similarly, in a mouse model that was engineered to express CETP, the pharmacological inhibition of CETP, leading to increased HDL-cholesterol levels, suppressed sepsis-induced inflammation and improved survival." (PMID 34638523, 2021). "In conclusion, despite having no direct LPS binding and transfer property, human CETP worsens sepsis outcomes in mice by altering the protective effects of plasma lipoproteins against endotoxemia, inflammation, and infection." (PMID 33500240, 2021). "We hypothesize that plasma concentration of CETP influences the TLR4 expression attenuating the inflammatory response induced by LPS and polymicrobial sepsis." (PMID 27293313, 2016). "Thus, after CLP induced polymicrobial sepsis at 24 h and 48 h, the liver protein levels of TLR4 and of AOAH were determined and shown markedly decreased in CETP as compared to WT." (PMID 27293313, 2016).
Sepsis (continued). "In sepsis there is a reduction in plasma concentrations of lipoproteins, especially HDL-C, which is due in part to alterations in the activity of plasma proteins that modulate the metabolism of these lipoproteins, such as CETP." (PMID 27293313, 2016). "As the in vivo experiments revealed an influence of CETP on endotoxemia and CLP induced sepsis, we asked whether this would have an impact on cell activation in the TLR4 signaling cascade." (PMID 27293313, 2016). "Reductions in CETP concentrations in human patients with sepsis are more pronounced in non-survivors." (PMID 23039379, 2012). "Emerging research also underscores the potential of CETP inhibitors in treating various conditions where inflammation is critical, including neurodegenerative diseases such as Alzheimer’s disease, age-related macular degeneration (AMD), and severe inflammatory states such as sepsis." (PMID 39057711, 2024). "In both WT and CETPTg mice, sepsis triggered a rapid and persistent elevation of LPS mass concentration in the plasma, with similar observations whether CETP was expressed or not." (PMID 33500240, 2021). "The negative correlation between CETP mass and HDL-C demonstrated by us corroborates the importance of the CETP variant rs1800777 (allele A) for the reduction of HDL levels in patients with sepsis." (PMID 30425299, 2018). "Interestingly, CETP mass showed a significantly negative correlation to HDL levels measured at sepsis admission (Spearman’s correlation = −0.555, R2 = 0.197, P = 0.011)." (PMID 30425299, 2018). "Also, Grion and colleagues showed that, in patients with sepsis, CETP is decreased in nonsurvivors as compared to survivors." (PMID 27293313, 2016). "In vitro experiments demonstrated that CETP inhibition significantly promoted the activation of proinflammatory signaling in peripheral blood mononuclear cells and THP1 cells in the absence of HDL; this may represent a mechanism responsible for improved bacterial clearance during sepsis." (PMID 38646937, 2024). "However, cholesteryl ester transfer protein inhibitors (CETP inhibitors), such as anacetrapib, have a more significant impact on increasing HDL-C than on reducing LDL-C and may have therapeutic effects on sepsis." (PMID 37621565, 2023). "Because both IL-6 and IL-10 were found in the present study to be increased in CETPTg mice, the consequences of CETP on clinical outcome in relation with cytokine expression should be considered with caution and may not be restricted to sepsis and LPS clearance." (PMID 33500240, 2021).
type 2 diabetes (37 papers, 2005 to 2025). "At the same time, the relevance between CETP gene polymorphisms and MS components, such as hypertension, type 2 diabetes, and low HDL-C has been studied." (PMID 28629169, 2017). "Genetically downregulated SGLT2 signaling and genetically lowered CETP activity are associated with additively lower lifetime risk of metabolic outcomes by way of significantly decreased glycated hemoglobin levels and lower incidence of type-2 diabetes." (PMID 37398493, 2023). "Patients affected by type 2 diabetes showed increased CETP activity; whether CETP levels are associated with changes of lipid profile during weight loss has not been described yet." (PMID 33686615, 2021). "Therefore, we decided to discover whether the effects of sesame, canola, and sesame-canola oils on blood lipids and glycemic control markers are conditioned by the CETP TaqIB polymorphism in patients with type 2 diabetes and healthy people." (PMID 33123324, 2020). "The magnitude and effect direction of the protein concentration (pQTL) weighted analysis were consistent with the LDL-C, HDL-C, and TG weighted analyses, which additionally suggested lower CETP protected against type 2 diabetes (T2DM) incidence." (PMID 34561430, 2021). "It was reported that fasting LDL-C levels were positively related to plasma CETP mass in patients with type 2 diabetes treated with atorvastatin." (PMID 34222380, 2021). "For example, concomitant presence of CETP B1, NOS3 T and ANGPTL8 T alleles augments the risk of both CHD and type 2 diabetes." (PMID 32000781, 2020). "The characteristic hypertriglyceridaemia observed in patients with type 2 diabetes stimulates CETP, leading to the preferential formation of triacylglycerol-rich small, dense LDL particles over larger ones." (PMID 25725623, 2015). "This is in full accordance with previous findings of a prolonged caloric restriction which resulted in a marked decrease in hepatic TG content and plasma CETP levels in obese type 2 diabetic patients." (PMID 24086738, 2013). "Conversely, relationships between CETP and plasma TG have been described in patients with type 2 diabetes, in which CETP protein and activity were positively associated with plasma TG." (PMID 23801661, 2013). "In conclusion, our findings suggest that genetic variation at the CETP gene may contribute to the heterogeneity in responsiveness of some metabolic traits to dietary oil treatments in patients with type 2 diabetes." (PMID 33123324, 2020). "The aim of the present study was to assess whether a liraglutide-induced reduction in hepatic triglyceride content would be accompanied by a reduction in circulating CETP concentration in patients with type 2 diabetes." (PMID 31292457, 2019). "The qualitative lipoprotein abnormalities observed in patients with type 2 diabetes, such as increased triacylglycerol content of LDL and HDL particles, indicate increased CETP activity." (PMID 25725623, 2015). "The main factor responsible for the increased CETP activity in type 2 diabetes is the augmented pool of triacylglycerol-rich lipoproteins (mainly VLDL), which directly stimulate CETP." (PMID 25725623, 2015). "In type 2 diabetes the triglyceride level is increased, which is due to multiple factors related to insulin and carbohydrate metabolism, LPL activity, CETP activity..." (PMID 15636639, 2005). "This highlights a potential drug repurposing opportunity, where CETP inhibitors, which are currently in clinical trials for cardiovascular disease, can be combined with SGLT2 inhibitors to create a combination therapy to treat type 2 diabetes." (PMID 38962682, 2024). "In both patients with type 2 diabetes and healthy people, there was no significant change in outcomes based on the CETP TaqIB genotypes for all three treatment periods (P > 0.05)." (PMID 33123324, 2020).
type 2 diabetes (continued). "CETP TaqI B and APOE HhaI polymorphism may not be associated with type II diabetes mellitus in North Indian population, however CETP TaqI B polymorphism may be associated with hypertension along with T2DM." (PMID 15992403, 2005). "CETP TaqI B and APOE HhaI polymorphism may not be associated with type II diabetes mellitus in north Indian population, however CETP TaqI B polymorphism may be associated with certain complications along with T2DM." (PMID 15992403, 2005).
Hypertension (22 papers, 2005 to 2024). The presence of chronic increased pressure in the systemic arterial system. "Among the CETP inhibitors, however hypertension was the most important adverse event associated with torcetrapib use as compared to the control arm (18.7% vs 7.5%; p = 0.001)." (PMID 24728455, 2014). "Some studies have linked CETP polymorphisms to cardiovascular disease, hypertension, and even longevity." (PMID 16623947, 2006). "The association between CETP and hypertension has been explored in animals and humans." (PMID 36551995, 2022). "For instance, a variant of the cholesteryl ester transfer protein in humans has been linked to larger high- and low-density lipoprotein particle sizes, which may decrease hypertension and cardiovascular disease, therein promoting longevity." (PMID 30046050, 2018). "Secondly, actual gene responsible/protective for hypertension may be different which is in linkage disequilibrium with CETP TaqI B polymorphism." (PMID 15992403, 2005). "Still, an increased expression of SVEP1, NRP1, RNASE1, QSOX1, and GKN1, along with decreased expression of XYLT2, CFH, LEP, and CETP serum levels were found in patients with hypertension." (PMID 37792298, 2023). "Interactions between the three CETP inhibitors and these predicted off-targets show potential additional contributions to the side-effects of hypertension, inflammation and cancer." (PMID 19436720, 2009). "Our predications are consistent with current clinical studies on all three CETP inhibitors, highlighting the interrelationship of multiple biological processes involved in hypertension, infection and cancer." (PMID 19436720, 2009). "The consumption of policosanol for 8 weeks by healthy female subjects with pre-hypertension resulted in lower blood pressure (BP) and CETP ability by elevating the HDL/apoA-I contents and enhancing the HDL functionalities, including cholesterol efflux and insulin secretion." (PMID 36982259, 2023). "The consumption of policosanol for 8 weeks by healthy female subjects with pre-hypertension resulted in a lower blood pressure and CETP ability by elevating the HDL/apoA-I contents and enhancing the HDL functionalities, including cholesterol efflux and insulin secretion." (PMID 36982259, 2023). "In addition, we analyzed polymorphic variants searching for haplotype blocks and potential interactions of CETP gene alleles with traditional CAD risk factors such as smoking, hypertension, and plasma lipid disorders." (PMID 30178218, 2018). "Many reports showed that CETP, LIPC and LIPG were associated with HDL and LDL and that MTHRR had known main effects for LDL and blood pressure, NR1I3 for lipid metabolism, PLTP for LDL, FOXO1 for LDL and hypertension, SMAD9 for hypertension, and CSMD1 for SBP." (PMID 27104857, 2016). "However, clinical studies indicated that one CETP inhibitor, Torcetrapib, has deadly off-target effects as a result of hypertension, and hence it has been withdrawn from phase III clinical trials." (PMID 19436720, 2009). "However, clinical studies have revealed that one of the CETP inhibitors, Torcetrapib, has deadly off-target effects as a result of hypertension and consequently was withdrawn from phase III clinical trial." (PMID 19436720, 2009). "In summary, most of the putative off-targets for CETP inhibitors are involved in interconnected lipid metabolism and signaling networks which activate or mediate various biological process such as hypertension, stress regulation, immune response and cell death." (PMID 19436720, 2009). "A circulating CETP level was unlikely to cause hypertension." (PMID 36551995, 2022). "Thus, it is more likely that the side-effect of CETP inhibitors is modulated by a combination of biological controls involved in many physiological processes such as cell proliferation, inflammation and hypertension." (PMID 19436720, 2009). "However, no causal relationship was found between CETP and hypertension or T2D." (PMID 39193372, 2024).
Hypertension (continued). "The circulating plasma CETP activity was not related to the change in systolic and diastolic blood pressure in a large community-based study with 1307 participants free from hypertension and cardiovascular disease with a mean age of 48 years old." (PMID 36551995, 2022).